VSX2 (visual system homeobox 2)
Description:
Acts as a transcriptional regulator through binding to DNA at the consensus sequence 5'-[TC]TAATT[AG][AG]-3' upstream of gene promoters. Plays a significant role in the specification and morphogenesis of the sensory retina (By similarity). May play a role in specification of V2a interneurons during spinal cord development (By similarity). Mediates differentiation of V2a interneurons by repression of motor neuron gene transcription, via competitively binding to response elements that are activated by the ISL1-LHX3 complex, such as VSX1. Acts as a positive transcriptional regulator of NXNL1; regulation is significantly increased in synergy with VSX1 (By similarity). Acts as a negative transcriptional regulator of MITF (By similarity). Represses SAG transcription by competitive inhibition of ISL1-LHX3 response elements. Binds to the photoreceptor conserved element-1 (PCE-1) in the promoter of rod photoreceptor arrestin SAG and acts as a transcriptional repressor (By similarity). Involved in the development of retinal ganglion cells (RGCs) which leads to release of SHH by RGCs, promoting Hedgehog signaling and subsequent proliferation of retinal progenitor cells (By similarity). Participates in the development of the cells of the inner nuclear layer, by promoting postnatal differentiation of bipolar cells with a comparable inhibition of rod cell differentiation (By similarity). May play a role in the maintenance of neural retina identity during development by regulation of canonical Wnt genes and CTNNB1 localization, suggesting a role in the regulation of canonical Wnt signaling.
Synonyms: CHX10; HOX10; RET1; MCOP2; MCOPCB3
Tractability: No criterion of Open Targets' tractability assessment is met for any kind of drug.
Gene: Protein-coding gene on chromosome 14 (74,239,449 to 74,262,738, forward strand). Ensembl gene ENSG00000119614.
Subcellular location: Nucleus
Gene Ontology:
Molecular function: DNA-binding transcription repressor activity, RNA polymerase II-specific; protein binding; RNA polymerase II transcription regulatory region sequence-specific DNA binding; sequence-specific double-stranded DNA binding; DNA-binding transcription factor activity, RNA polymerase II-specific; DNA binding
Biological process: negative regulation of transcription by RNA polymerase II; regulation of transcription by RNA polymerase II; regulation of DNA-templated transcription
Cellular component: chromatin; nucleus; cytoplasm
Genetic constraint (gnomAD): Loss-of-function variants: 28 observed, 28.43 expected, observed/expected ratio (o/e) 0.98, 90% interval 0.73 to 1.35. The synonymous counts are far from expectation, so gnomAD's model fits this gene poorly and the ratio says little. Missense variants: 506 observed, 434.78 expected, observed/expected ratio (o/e) 1.16, 90% interval 1.08 to 1.25. Synonymous variants: 243 observed, 192 expected, observed/expected ratio (o/e) 1.27, 90% interval 1.14 to 1.41.
Homologues: Orthologues: chimpanzee VSX2 (99% identical), macaque VSX2 (99% identical), rat Vsx2 (97% identical), mouse Vsx2 (97% identical), dog VSX2 (96% identical), guinea pig VSX2 (96% identical), pig VSX2 (95% identical), rabbit VSX2 (94% identical), zebrafish vsx2 (71% identical), tropical clawed frog vsx2 (61% identical). Paralogues in human: ALX4 (27% identical), ARX (27% identical), RAX (24% identical), UNCX (22% identical), ALX3 (22% identical), PITX2 (22% identical), SHOX2 (22% identical), ALX1 (22% identical), SHOX (21% identical), OTP (21% identical), PAX7 (21% identical), PITX1 (21% identical), and 38 more.
Diseases named in the same sentence as VSX2 in open-access papers:
VSX2 is named in the same sentence as 58 diseases in open-access papers, as found by Europe PMC text mining. Sharing a sentence is not in itself a finding about the gene and the disease. The quoted sentences say what the papers report.
microphthalmia (36 papers, 2007 to 2025). Congenital or developmental anomaly in which the eyeballs are abnormally small. "Mutations in the Vsx2/VSX2 gene lead to microphthalmia in humans and mice due to a defect in retinal progenitor cell proliferation." (PMID 38994775, 2024). "Mutations in the Vsx2 gene and deletion of the mR0-37 Vsx2 SE module leads to microphthalmia due to defects in retinal progenitor cell proliferation." (PMID 38994775, 2024). "Further evidence indicates this is a common pathway in microphthalmia from the VSX2-associated microphthalmia dataset." (PMID 38821055, 2024). "In both our patients and VSX2-associated microphthalmia, we observed common upregulation of ECM components such as collagen and laminin family proteins, fibronectin, and hyaluronan and proteoglycan-link proteins that play significant roles in eye development." (PMID 38821055, 2024). "Previous studies of VSX2-associated microphthalmia also reported reduced diameters of patient OVs coupled with reduced cell proliferation." (PMID 38821055, 2024). "(iii) Finally, here we show that the mutation of the paralogs vsx1 and vsx2.2 results in severe microphthalmia in medaka larvae." (PMID 37227126, 2023). "Pathogenic variants in VSX2 are associated with isolated microphthalmia and microphthalmia with coloboma." (PMID 37628625, 2023). "A nonsense mutation in Vsx2 (Y176stop) turned to be the molecular cause of the phenotype exhibited by the classical mutant mice ocular retardation (or), which displays microphthalmia and optic nerve aplasia." (PMID 37227126, 2023). "Mutations in human and mouse VSX2/Vsx2 lead to microphthalmia because it is required for retinal progenitor cell proliferation." (PMID 35017532, 2022). "Their development in vitro has been found to mirror that of the human eye and these early organoids have been used to effectively model microphthalmia caused by a VSX2 variant." (PMID 32973457, 2020). "Ocular retardation (Or) mice with a null mutation of Vsx2/Chx10 have microphthalmia, thin retinas, and optic nerve aplasia." (PMID 32111086, 2020). "Visual system homeobox 2 (vsx2) is a key transcription factor involved in neural retinal development, and mutations in this gene can cause microphthalmia." (PMID 32010191, 2019). "Biallelic mutations in VSX2 are thought to account for 2% of isolated microphthalmia, and were identified in 1.5% of all MAC (microphthalmia, anophthalmia and coloboma) cases in a screening of >880 samples." (PMID 31416264, 2019). "Human patients with mutations in Vsx2 present clinically with microphthalmia, iris colobomas, cataracts, and congenital blindness." (PMID 25927996, 2015). "Genes down-regulated in rx3-/- mutants are mostly associated with eye diseases, including microphthalmia (rx2, rx3, vsx2, six6b and aldh1a3) and oculoauricular syndrome (hmx1)." (PMID 25266257, 2014). "Here, we show that genes previously linked with microphthalmia, including aldh1a3, rx2, six6b, vsx2, and recently mab21l2 with anophthalmia, are constitutive elements of an Rx3-regulated gene network." (PMID 25266257, 2014). "Severe microphthalmia is associated with mutations in the retinal-expressed visual system homeobox 2 (Vsx2) gene, but how Vsx2 controls retinal development, and ultimately eye formation, has remained unclear." (PMID 23028343, 2012). "Our observations thus far reveal the essential and complex role of Mitf misregulation in causing microphthalmia and in interfering with retinal development in the Vsx2 mutant backgrounds." (PMID 23028343, 2012). "To better understand the role of Mitf in microphthalmia and the retinal defects caused by the Vsx2 mutations, we generated compound mutants homozygous for the Vsx2 alleles and heterozygous for the Mitf mi allele (mi/+)." (PMID 23028343, 2012). "Humans with missense mutations in these regions of VSX2 have microphthalmia, suggesting both regions are critical for function." (PMID 23028343, 2012).
microphthalmia (continued). "Homozygous mutations in VSX2 were identified in two out of five consanguineous families with isolated microphthalmia." (PMID 21976963, 2011). "Mutations in VSX2 represent an important cause of autosomal recessive microphthalmia in consanguineous pedigrees." (PMID 21976963, 2011). "VSX2 mutations were identified in 33% (2 out of 6) of consanguineous families with isolated microphthalmia." (PMID 21976963, 2011). "We screened 95 probands with syndromic or isolated developmental ocular conditions (including 55 with anophthalmia/microphthalmia) for mutations in VSX2." (PMID 21976963, 2011). "In the mouse, homozygous-null mutations in vsx2 cause microphthalmia, but in these small eyes bipolar cell fate is severely impaired." (PMID 19344499, 2009). "Interestingly, eye size, lens degeneration, and defective retinal morphology are frequently correlated in humans with anopthalmia/microphthalmia caused by mutations in sox2 and vsx2/chx10." (PMID 23437360, 2013). "This hypothesis is supported from previous studies into VSX2-associated microphthalmia." (PMID 38821055, 2024). "We also replaced mR0-37 with the orthologous sequence from the human VSX2 SE (hR0-36) and showed functional rescue of microphthalmia." (PMID 38994775, 2024). "By inserting the human sequence of one VSX2 SE module into a mouse with microphthalmia, eye size was rescued." (PMID 38994775, 2024). "Our observations are also in contrast to previous reports in zebrafish using antisense oligonucleotides or morpholinos against vsx2, which show microphthalmia and optic cup malformations." (PMID 37227126, 2023). "The phenotypic analysis of or mutants, as well as the examination of human patients with hereditary microphthalmia, revealed an essential role for Vsx2 in neuro-epithelial proliferation and bipolar cells differentiation." (PMID 37227126, 2023). "The strong microphthalmia and abnormal specification of the neural retina reported in vsx2 mutant mice are in contrast to our observation that in vsxKO embryos/larvae optic cup identity is normally established and maintained." (PMID 37227126, 2023). "This is in contrast to the Vsx2 orJ mutant mouse strain that has microphthalmia and lacks bipolar neurons." (PMID 35017532, 2022). "Further investigation into the molecular etiology of microphthalmia, using the same patient hiPSC line, highlighted the transcriptional regulatory role of VSX2." (PMID 32973457, 2020). "In humans, a single base substitution in the DNA-recognition helix of the VSX2 homeobox, a deletion of the homeobox, and a mutation of the CVC domain cause microphthalmia." (PMID 32111086, 2020). "Despite limited work, the use of patient hiPSC-derived optic vesicles has already provided some insight into the pathophysiology of VSX2-related microphthalmia and highlighted potential therapeutic targets." (PMID 32973457, 2020). "Vsx2-dependent microphthalmia also occurs in homozygous ocular retardation J mice (MGI symbol: orJ), which harbor a nonsense mutation in the homeodomain." (PMID 23028343, 2012). "This is only the second report of a missense mutation predicted to affect the VSX2 CVC motif and resulting in a microphthalmia phenotype." (PMID 21976963, 2011). "Treatment of zebrafish embryos with antisense oligonucleotides to vsx2 RNA showed a concentration-dependent reduction in the size of the eyes, resembling mouse and human microphthalmia in vsx2 mutants." (PMID 19344499, 2009). "A number of mutations of the VSX2 gene have been reported in patients from West and South Asia to be associated with autosomal-recessive anophthalmia/microphthalmia, with or without iris coloboma and other ocular anomalies." (PMID 32111086, 2020). "As an isogenic iPSC-derived disease model of VSX2-associated microphthalmia has not been produced alongside these patient models, it is harder to predict the causative nature of the VSX2 mutation." (PMID 32973457, 2020).
microphthalmia (continued). "As a proof-of-principle, the authors examined the role of a key transcription factor, visual system homeobox 2 (VSX2), using iPSC-derived optic vesicle-like structures that were obtained from a patient with microphthalmia caused by an R200Q mutation in the VSX2 homeodomain region." (PMID 26880972, 2016). "Mutations in VSX2 are associated with autosomal recessive anophthalmia/microphthalmia (A/M), with or without iris coloboma and other ocular anomalies; eleven families have been described with eight different VSX2 mutations." (PMID 21976963, 2011). "However, mutations in VSX2, CRYBA4, OTX2, and RAX have been detected in about 2%–3% patients with microphthalmia, anophthalmia, and coloboma." (PMID 20057906, 2009). "Similarly, we note the surprising finding of NM_182894.2:c.456-6C > G variant in VSX2 causing ectopia lentis rather than the established microphthalmia phenotype, which supports a previously published case report." (PMID 32552793, 2020). "The second mutation, c.249delG (p.Leu84SerfsX57), was identified in an Iranian family with microphthalmia; this mutation has been previously reported and is predicted to generate a severely truncated mutant protein completely lacking the VSX2 homeodomain, CVC domain and COOH-terminal regions." (PMID 21976963, 2011). "In animal models, the disruption of Visual System Homeobox 2 (VSX2) function results in severe eye and retinal abnormalities, such as microphthalmia, decreased neural retina thickness, and ectopic RPE differentiation." (PMID 36359825, 2022). "Mutations in several genes have been reported in patients with microphthalmia and/or coloboma, including BMP4 (OMIM 112262), VSX2 (CHX10; OMIM 142993), CRYBA4 (OMIM 123631), OTX2 (OMIM 600037), RAX (OMIM 601881), SIX6 (OMIM 606326), and SOX2 (OMIM 184429)." (PMID 20057906, 2009). "In line with this, in Vsx2 mutant mice has been shown that neural retinal identity defects and microphthalmia (but not bipolar cells differentiation) can be partially restored by simply deleting a cell cycle gene." (PMID 37227126, 2023).
coloboma (9 papers, 2007 to 2024). An abnormality in which a part of a structure in one or both eyes is missing. "Cyp1b1 regulated the expression of vsx2, pax6, and shh, genes clinically associated with colobomas." (PMID 28192799, 2017).
retinal degeneration (9 papers, 2015 to 2025). Degeneration of the retina. "In the case of the retina, Dicer1 KO in mouse RPC (thanks to the use of a Cre recombinase targeted by Vsx2/Chx10 regulatory sequences) has no obvious phenotype caused by developmental impairments but is characterized for a retinal degeneration at the second postnatal week." (PMID 36769311, 2023).
liposarcoma (2 papers, 2020 to 2022). A usually painless malignant tumor that arises from adipose tissue. "These candidates include immunoglobulin heavy chain, translocated in liposarcoma (TLS) and visual system homeobox 2 (VSX2)." (PMID 32998289, 2020).
acute myeloid leukemia (1 paper, 2025). Acute myeloid leukemia (AML) is a group of neoplasms arising from precursor cells committed to the myeloid cell-line differentiation. "It is often used as a diagnostic factor for acute myeloid leukemia, but its role in the retina is mostly unknown except for its interaction with chx10/vsx2 in MG." (PMID 40308558, 2025).
Axenfeld-Rieger syndrome (1 paper, 2012). Axenfeld-Rieger syndrome (ARS) is a generic term used to designate overlapping genetic disorders, in which the major physical condition is anterior segment dysgenesis of the eye. "It is also possible that these alleles could exhibit dominant negative activity if Vsx2 activity requires dimerization, similar to DNA binding mutations in the homeodomain protein Pitx2, which are linked to Axenfeld-Rieger syndrome." (PMID 23028343, 2012).
colon cancer (1 paper, 2025). "Indeed, 6 out of 10 leading TFs have direct evidence and some experimental validation of their involvement in colon cancer risk and progression: ZNF334, FOXD2, FOXD3, POU3F3, NR1H4, and VSX2." (PMID 41114645, 2025).
Down syndrome (1 paper, 2019). "If there was accelerated development in the Down syndrome retinas, we would expect to see a greater number of VSX2+ bipolar cells, more mature photoreceptors (RCVRN) and an increase in VGLUT/SLC17A7 labeling, but we do not see these changes." (PMID 30842553, 2019).
ocular sarcoidosis (1 paper, 2022). A leading cause of inflammatory eye disease is sarcoidosis. "The rs149564368 (g.74267460C > T) of VSX2 was associated with higher susceptibility to ocular sarcoidosis, and the RAX2 rs76076446 is associated with susceptibility to macular thickness." (PMID 35656327, 2022).
retinal dystrophies (1 paper, 2023). "There was evidence for an interaction effect between common genetic variants, VSX2 involved in eye development and PRPH2 known to be involved in retinal dystrophies." (PMID 36848389, 2023).
ZIKV infection (1 paper, 2023). "We observed that MITF-positive RPE cell layer and internal VSX2 expressing neural retinal cells are permissive to ZIKV infection, suggesting a broader ZIKV tropism, which can result in retinal abnormalities in a developing eye." (PMID 36680182, 2023).
retinal disorder (2 papers, 2022 to 2024). Any disease or disorder of the retina. "This is useful for identifying transcription factor-binding sites and searching for genomic variants that may alter VSX2 expression in human with retinopathies." (PMID 38994775, 2024). "The current signed-off version of Genomics England’s PanelApp Retinal Disorders virtual panel gene list (version v2.195) includes all six main CACD genes, plus CRX, NR2E3, NRL, RAX2 and also VSX2, but as low-evidence gene (red list)." (PMID 35656327, 2022).
VSX2 also shares sentences with these, for which no sentence is quoted: retinoblastoma (13 papers); Anophthalmia (10); tumor (8); cancer (2); cyst (2); ectopia lentis (2); Adult onset (1); African Trypanosomiasis (1); aniridia (1); Apnea (1); autonomic dysreflexia (1); Bradycardia (1); breast carcinoma (1); cataract (1); congenital blindness (1); developmental eye defect (1); diabetes (1); female infertility (1); glioma (1); hyperandrogenism (1); Hyperglycemia (1); inflammatory bowel disease (1); Intellectual disability (1); iris coloboma (1); ischemic stroke (1); lens agenesis (1); lung adenocarcinoma (1); melanoma (1); myopia (1); neurodegenerative disease (1).
A further 16 diseases each share a sentence with VSX2 in 1 paper.